UCA1 (urothelial cancer associated 1)
Synonyms: LINC00178; CUDR; UCAT1; onco-lncRNA-36; NCRNA00178
Gene: Long non-coding RNA gene on chromosome 19 (15,828,206 to 15,836,328, forward strand). Ensembl gene ENSG00000214049.
Gene Ontology:
Biological process: regulation of gene expression
Diseases named in the same sentence as UCA1 in open-access papers:
UCA1 is named in the same sentence as 165 diseases in open-access papers, as found by Europe PMC text mining. Sharing a sentence is not in itself a finding about the gene and the disease. The quoted sentences say what the papers report.
bladder cancer (254 papers, 2011 to 2025). "in 2021, which included seven studies, it was reported that urinary lncRNA UCA1 achieved a diagnostic sensitivity of 83%, specificity of 86%, and an AUC value of 0.86 in bladder cancer." (PMID 41179679, 2025). "This system successfully detected individual UCA1 molecules under controlled experimental conditions, highlighting its potential as a sensitive, specific, and label-free diagnostic tool for early bladder cancer detection using urine samples." (PMID 40868379, 2025). "Several ncRNAs involved in bladder cancer progression have been identified, for instance urothelial carcinoma associated 1 (UCA1) and ZEB2-AS1 which are up-regulated in bladder tumours." (PMID 40461454, 2025). "Urothelial cancer-associated 1 (UCA1) is a lncRNA, first found deregulated in bladder cancer, and many studies have exposed its oncogenic effects in more tumors since." (PMID 38534790, 2024). "The lncRNA urothelial carcinoma-associated 1 (UCA1) was elevated in bladder cancer tissues, according to our prior work." (PMID 37215997, 2023). "Urothelial carcinoma-associated 1 (UCA1) is a lncRNA that has been previously found to influence the cell cycle, drug resistance, apoptosis, proliferation, migration, and invasion of bladder cancer cells." (PMID 36605618, 2023). "Urothelial cancer associated 1 (UCA1) is an long non-coding RNA (lncRNA) involved in the development of bladder cancer, gastric cancer, and colorectal cancer." (PMID 37076497, 2023). "Urothelial cancer-associated 1 (UCA1), which is thought to play a role in bladder cancer progression, was significantly upregulated in TSCC and OSCC." (PMID 37733767, 2023). "The bladder cancer-specific lncRNA UCA1 (urothelial cancer associated 1) was also associated with tumor progression, invasiveness, and chemoresistance in bladder cancer cell lines, by competing with tumor-suppressing miRNAs and modulating signaling pathways." (PMID 36903656, 2023). "Long noncoding RNA urothelial carcinoma-associated 1 (LncRNA UCA1) is a potential tumor biomarker for bladder cancer diagnosis and prognosis, and it increases bladder cancer cell proliferation, migration, and invasion via the glycolysis pathway." (PMID 37215997, 2023). "LncRNA urothelial cancer-associated 1 (UCA1) is a noncoding RNA first identified to be associated with the tumorigenesis of bladder cancer." (PMID 35565245, 2022). "Urothelial cancer associated 1 (UCA1) is one of the lncRNA associated with bladder cancer progression." (PMID 36685879, 2022). "LncRNA urothelial cancer associated 1 (UCA1) is upregulated and positively correlated with a poor prognosis in bladder cancer patients." (PMID 36499136, 2022). "A long noncoding R.N.A. is called Urothelial cancer associated 1 (RNA-UCA1) increases in bladder cancer and regulates the expression of several genes participating in tumorigenesis." (PMID 36463254, 2022). "In EVs obtained from bladder carcinoma cells raised under hypoxic conditions, the content of urothelial carcinoma associated-1 (UCA1), a hypoxia-responsive lncRNA, was found to be enriched compared with EVs obtained from normoxic bladder carcinoma cells." (PMID 35966580, 2022). "LncRNA urothelial carcinoma‐associated 1 (UCA1) acts as an oncogene in a series of cancer types, such as gastric cancer, bladder cancer and colorectal cancer." (PMID 33743811, 2021). "UCA1 (Urothelial Cancer Associated 1), is a lncRNA initially identified in a bladder cancer cell line." (PMID 34055770, 2021). "Urothelial carcinoma associated 1 (UCA1) was initially identified in bladder cancer by high-throughput RNA sequencing, and is associated with the progression of bladder cancer." (PMID 33777227, 2021). "lncRNA urothelial cancer-associated 1 (UCA1) was shown to be upregulated in cisplatin-resistant bladder cancer cells compared to sensitive cells." (PMID 34502361, 2021).
bladder cancer (continued). "UCA1 (urothelial carcinoma associated 1) is a lncRNA that was firstly identified in human bladder carcinoma, whose expression is also found to be elevated in many other cancers." (PMID 33565716, 2021). "Urothelial carcinoma associated 1 (UCA1) is a non-coding RNA that has been detected in bladder cancer for the first time." (PMID 34425750, 2021). "UCA1 has three exons that encode a 2.2-kb and 1.4-kb isoform, and the 1.4-kb isoform was first identified as a urine marker in bladder cancer." (PMID 33743811, 2021). "The lncRNA, urothelial carcinoma associated 1 (UCA1), located at the human chromosome 19p13.12, was discovered in bladder cancer." (PMID 34238213, 2021). "Taken together, UCA1 has relatively high sensitivity, specificity and AUC, and it can be regarded as the most potential diagnostic biomarker for bladder cancer." (PMID 34422802, 2021). "Dissection of fifteen up-regulated lncRNAs associated with tumor size of bladder cancer, UCA1 has relatively high sensitivity, specificity and AUC, and it can be considered as the most potential diagnostic biomarker for bladder cancer." (PMID 34422802, 2021). "The lncRNA urothelial cancer-associated 1 (UCA1) was first identified from bladder cancer cell line BLZ-211." (PMID 34733326, 2021). "Another study has indicated that circFARSA, circSHKBP1, circBANP, and lncRNA urothelial carcinoma-associated 1 (UCA1) are correlated with the diagnosis and prognosis of bladder cancer." (PMID 33816529, 2021). "Hypoxic exosomes from bladder cancer cells carry urothelial cancer-associated 1 (UCA1) that augment tumor growth through epithelial-mesenchymal transition." (PMID 32499786, 2020). "Urothelial cancer-associated 1 (UCA1) has been found to be overexpressed in bladder cancer cell lines and induce less apoptosis after DDP treatment, partially through activating the wingless-type MMTV integration site family member 6 (Wnt6) signaling pathway." (PMID 32122355, 2020). "Other exosomal-transferred lncRNAs that are implicated in cancer cells during hypoxia include UCA1 in bladder cancer for promoting tumor growth and EMT, and CCAT2 for glioma’s resistance to apoptosis and angiogenesis." (PMID 32370770, 2020). "On the other hand, miR-195, which is regulated by Urothelial Cancer Associated 1 (UCA1) targets ARL2 in bladder cancer (Li H.-J." (PMID 32426352, 2020). "Urothelial cancer associated 1 (UCA1) is involved in regulation of mitochondrial metabolism through miR-195/ARL2 pathway in bladder cancer." (PMID 31956395, 2020). "The expression of the long noncoding RNA (lncRNA) urothelial carcinoma-associated 1 (UCA1) in embryonic tissues is higher than that in most cancer tissues, such as bladder cancer, indicating that RNA is a carcinoembryonic antigen." (PMID 33680939, 2020). "It has been reported that overexpression of lncRNA urothelial carcinoma-associated 1 (UCA1) promoted the expression of GLS2 in human bladder cancer cells." (PMID 35006436, 2020). "For example, the urothelial cancer-associated 1 (UCA1) lncRNA is upregulated in cisplatin-resistant bladder cancer, which activates Wnt signaling in a Wnt6-dependent manner." (PMID 33375322, 2020). "It is demonstrated that lncRNA urothelial carcinoma-associated 1 (UCA1) is enriched in hypoxic bladder cancer cell-derived exosomes, and hypoxic exosomal lncRNA UCA1 promotes tumor growth and progression though accelerating EMT." (PMID 31438991, 2019). "For example, lncRNA urothelial cancer-associated 1 (UCA1) was shown to be upregulated in cisplatin-resistant bladder cancer cells compared to sensitive cells." (PMID 34322663, 2019). "Urothelial cancer‐associated 1 (UCA1) is first identified as an oncogenic lncRNA in bladder cancer, which has been reported to regulate bladder cancer cell proliferation, migration, invasion chemoresistance, and metabolism." (PMID 31695578, 2019).
bladder cancer (continued). "More importantly, the diagnostic meta-analysis concluded that abnormally expressed UCA1 can function as potential diagnostic markers for bladder cancer." (PMID 29899709, 2018). "Focusing on CRC cells, the interaction of UCA1 with miR-143, first reported in bladder cancer cells, was confirmed and implicated UCA1 as an upstream effector of mTOR activation and as a regulator of K-Ras expression." (PMID 30441811, 2018). "Urothelial cancer-associated 1 (UCA1) was first thought to participate in bladder cancer invasion and progression." (PMID 29416703, 2018). "In current study, the DOR value was calculated to be 39.65, suggesting a moderate diagnostic accuracy of UCA1 for bladder cancer diagnosis." (PMID 29899709, 2018). "Urothelial carcinoma-associated 1 (UCA1) is a lncRNA that was originally cloned and identified in the bladder cancer cell line BLZ-21129." (PMID 30349036, 2018). "Since five studies investigated diagnostic value of UCA1 for bladder cancer, a meta-analysis was performed based on UCA1." (PMID 29899709, 2018). "For example, lncRNA urothelial cancer-associated 1 (UCA1) has been shown to overexpress in bladder cancer, and the high expression of UCA1 frequently enhanced the invasive and migratory capacity of bladder cancer cells." (PMID 29416735, 2018). "Urothelial cancer associated 1 (UCA1) lncRNA is highly expressed in bladder tumor tissues and has been used to distinguish bladder cancer from other urinary related diseases." (PMID 29719633, 2018). "Five studies investigated diagnostic value of lncRNA UCA1 for bladder cancer, but diagnostic accuracy differed greatly among these studies." (PMID 29899709, 2018). "lncRNA urothelial cancer-associated 1 (UCA1) was shown to play a pivotal role in bladder cancer progression and embryonic development." (PMID 30595764, 2018). "Urothelial Cancer Associated 1 (UCA1) was first discovered in bladder cancer and its long transcript is also the nominated Cancer Upregulated Drug-Resistant transcript (CUDR)." (PMID 30441811, 2018). "Urothelial cancer is associated 1 (UCA1), which is a long non-coding RNA length 1442 bp that was first cloned and identified in bladder cancer BLZ-211 cells." (PMID 29642505, 2018). "LncRNA urothelial cancer-associated 1 (UCA1) promoted bladder cancer cell migration and invasion via hsa-miR-145/ZEB1/2/FSCN1 pathway." (PMID 29899709, 2018). "The diagnostic significance of UCA1 expression in bladder cancer has been investigated by meta-analysis in recent studies." (PMID 29899709, 2018). "As a result of this, a diagnostic meta-analysis to assess the diagnostic performance of urine UCA1 in detecting bladder cancer was conducted." (PMID 28415640, 2017). "UCA1 (urothelial cancer associated 1), an lncRNA upregulated in several tumors (i.e., bladder cancer, tongue squamous cell carcinoma, breast cancer, and ovarian cancer), possesses two predicted binding sites for miR-1, a well-known tumor suppressor miRNA." (PMID 29147648, 2017). "Urine UCA1 has been reported as a potential novel diagnostic biomarker for bladder cancer in several studies, but their results are inconsistent." (PMID 28415640, 2017). "In current meta-analysis, we conducted the first diagnostic meta-analysis to assess the accuracy of urine UCA1 as a biomarker for bladder cancer." (PMID 28415640, 2017). "For instance, in bladder cancer, UCA1 is associated with sensitivity to drug therapy as knockdown of this lncRNA led to decreased chemosensitivity to a cisplatin/gemcitabine combination, which again involved a miRNA, in this instance miR-196a-5p." (PMID 28430163, 2017). "Urothelial carcinoma associated antigen 1 (UCA1) is a bladder cancer-specific lncRNA, with a total length of 1439 bp and is located in the 19p13.12." (PMID 28108736, 2017). "It has been revealed that the long non-coding RNAs (lncRNAs) urothelial cancer-associated 1 (UCA1) promotes glycolysis in bladder cancer cells via the mTOR/STAT3/HK-II cascade." (PMID 27823965, 2017).
bladder cancer (continued). "Urothelial Carcinoma Associated 1 (UCA1), which acts as oncogenic lncRNA and promotes bladder cancer progression, has been studied in a meta-analysis that up-regulated UCA1 was significantly corrected with LNM and poor OS in patients with various cancers." (PMID 28187755, 2017). "Urothelial carcinoma associated 1 (UCA1), mapping to chromosome region of 19p13.12, was initially discovered and identified in human bladder carcinoma." (PMID 29221199, 2017). "According to our results, urine UCA1 has greater diagnostic value in diagnosing bladder cancer, however further research studies with more well-designed and large sample sizes are required to confirm our findings." (PMID 28415640, 2017). "The lncRNA urothelial carcinoma-associated 1 (UCA1) is upregulated in bladder cancer and promotes the progression of bladder cancer." (PMID 28038452, 2017). "Urothelial Cancer Associated 1 (UCA1) is a lncRNA which was identified as highly upregulated in bladder cancer and has since been implicated in other cancers like colorectal, ovarian and renal carcinomas." (PMID 28715488, 2017). "An lnc RNA named urothelial carcinoma-associated 1 (UCA1) is found in tumors such as bladder cancers and lung cancer." (PMID 26949706, 2016). "Human urothelial carcinoma associated 1 (UCA1) was first reported to be over-expressed in bladder cancer and was suggested to serve as a biomarker for the diagnosis of bladder cancer." (PMID 27046651, 2016). "The lncRNA urothelial carcinoma associated 1 (UCA1) was originally identified as a urine marker encoding 1439 bp transcript in bladder cancer." (PMID 27977766, 2016). "Previous studied also showed that LncRNA-urothelial cancer associated 1 (UCA1) was highly expressed in bladder cancer tissues and cells, and it has been shown to play an important role in regulating aggressive phenotypes of bladder cancer cells." (PMID 27326854, 2016). "Urothelial carcinoma-associated 1 (UCA1) was originally identified as being dramatically upregulated in bladder cancer, and is known as a highly specific and sensitive biomarker for diagnosing bladder carcinoma." (PMID 25400658, 2014). "Long non-coding RNA urothelial carcinoma associated 1 (UCA1) was first identified in bladder cancer tissues." (PMID 24993775, 2014). "Despite the recent interest in UCA1 as a diagnostic marker for bladder cancer, little is known about its transcriptional regulation." (PMID 24069250, 2013). "In support, LncRNA urothelial carcinoma associated 1 (UCA1) regulates cell cycle distribution via CREB through PI3K-AKt dependent pathway in bladder carcinoma cells." (PMID 24312245, 2013). "Previously, our laboratory has identified that a lncRNA, Urothelial cancer associated 1 (UCA1), played an important role in bladder cancer." (PMID 24069250, 2013). "The elevated expression of UCA1 in bladder cancer and the existence of splicing variants strongly indicate that the transcriptional regulation of the UCA1 gene is tightly controlled." (PMID 24069250, 2013). "For example, the lncRNA urothelial cancer associated 1 (UCA1) has demonstrated roles in both embryonic development and is implicated in bladder cancer, supporting this concept." (PMID 21991387, 2011). "UCA1 has reasonably good sensitivity, specificity, and area under the curve (AUC), and it may be regarded the most viable diagnostic biomarker for bladder cancer." (PMID 39512820, 2024). "Additionally, in bladder cancer, the lncRNA urothelial cancer associated 1 (Uca1) reduces ROS levels by targeting miR-16, which in turn decreases GSH synthetase levels." (PMID 39595619, 2024). "For instance, Urothelial Cancer Associated 1 (UCA1) is a well-documented lncRNA in bladder cancer that promotes tumorigenic potential and drug resistance, and H19 RNA levels are found to be much higher in both primary and metastatic tumor than in normal tissues." (PMID 38846969, 2024).